PYGB (glycogen phosphorylase B)
Diseases named in the same sentence as PYGB in open-access papers (continued):
Sharing a sentence is not in itself a finding about the gene and the disease.
cancer (continued). "Studies have shown that EMT played a critical role in the cell growth, invasion and metastasis of cancer cells, which were consistent with the roles of PYGB in HCC growth and metastasis." (PMID 33324633, 2020). "Another study with gastric cancer cell lines found that PYGB activity and glycogen breakdown were increased upon serum starvation conditions, resulting in reduced apoptosis and cancer cell survival." (PMID 26882899, 2016). "Glycogen phosphorylase brain form (PYGB) was found to be important also in nutrient starvation conditions in cancer cell survival." (PMID 26882899, 2016). "This knowledge may pave the way for novel strategies aimed at targeting PYGB in cancer treatment, potentially improving therapeutic outcomes for patients with malignancies." (PMID 40458414, 2025). "Understanding the structural and regulatory properties of PYGB, especially in comparison to other glycogen phosphorylase isozymes, can provide insights into its unique functions in the brain and its contributions to cancer biology." (PMID 40458414, 2025). "The differences in the expression of PYGB in pan-cancer tissues and normal tissues were analyzed." (PMID 40458414, 2025). "Knocking down PYGB will inhibit the malignant phenotypes of cancer cells." (PMID 38334681, 2024). "Combined with pan-cancer analysis, we found that PYGB had the most significant impact on PC." (PMID 38483604, 2024). "There is increasing evidence suggesting that PYGB may be closely related to many human diseases, including cancer, diabetes, neurodegenerative diseases, and cardiovascular diseases." (PMID 38334681, 2024). "Recent evidence suggests that PYGB is involved in the tumorigenesis of many cancers." (PMID 38483604, 2024). "Next, we further used pan-cancer analysis to understand the effects of PYGB in tumors." (PMID 38483604, 2024). "In addition, PYGB is mainly located in the cytoplasm in cancer tissues, while 12% in normal tissues is located in the nucleus, on average." (PMID 38334681, 2024). "Finally, the PFS, OS, DSS, and DFS correlation with PYGB expression was investigated in the pan-cancer dataset." (PMID 38483604, 2024). "This study revealed that the multifocal expression of PYGB mainly appeared in the colorectal mucosa adjacent to the “de novo” carcinoma, and that the PYGB foci may serve as potential preneoplastic lesions of “de novo” colorectal carcinogenesis." (PMID 38334681, 2024). "Brain‐type glycogen phosphorylase (PYGB) could regulate multiple biological characteristics of cancer cells, such as proliferation, invasion, and apoptosis, and metastatic phenotypes of several cancers." (PMID 34609082, 2021). "Dysregulated expression of PYGB in a series of cancers was discovered in last two decades." (PMID 33324633, 2020). "High expression levels of glycogen phosphorylase B (PYGB) were reported in several cancers and might be served as a prognostic biomarker for cancer from precancerous lesions." (PMID 33324633, 2020). "However, the cancer-promoting mechanism and expression level of PYGB in cells or PC tissues have not been explored." (PMID 38483604, 2024). "The inhibition of PYGB activity and protein expression by 1g measured in the biochemical assays reported in this paper is well related to a reduction of U87MG cell proliferation both due to a decrease of cancer cell fuel and the modulation of the PI3k/Akt pathway." (PMID 35897773, 2022). "While all breast cells tested increased glycogen storage under hypoxia, glycogen utilization as promoted by the brain isoform of glycogen phosphorylase, PYGB, affects migration and invasion phenotypes only in cancer cells and not in normal-like epithelial cells." (PMID 31536495, 2019). "The research also indicates that silencing PYGB can impede the advancement of NSCLC, proposing that PYGB could serve as a novel biomarker and a potential molecular therapeutic target for this malignancy.Due to these findings, it is speculated that PYGB might promote cancer similar to early studies." (PMID 40458414, 2025).
tumor (11 papers, 2020 to 2025). "Further analysis demonstrated correlations between PYGB expression and immune infiltration, immune checkpoint expression, tumor mutation burden, and microsatellite instability in LC." (PMID 40458414, 2025). "We also found that high PYGB gene expression is closely associated with many tumor-related biological processes." (PMID 38483604, 2024). "PYGB overexpression was significantly associated with an aggressive tumor phenotype and poor prognosis of HCC patients." (PMID 33324633, 2020). "PYGB, by comparison, showed only weak correlations, including a marginal negative association with immune score, suggesting a more restricted influence on the tumor microenvironment than CAMK2A or CHMP4C." (PMID 41180485, 2025). "The association of PYGB with different diseases underscores its potential as a therapeutic target, as modulating its activity could impact tumor metabolism and growth." (PMID 40458414, 2025). "In HCC, PYGB is notably overexpressed and correlates with aggressive tumor phenotypes and poor prognosis." (PMID 40458414, 2025). "Given that LC is a highly immunogenic tumor, we analyzed the relationship between immune-related scores and PYGB expression." (PMID 40458414, 2025). "Recent research indicates that metabolic reprogramming driven by PYGB facilitates tumor growth in hypoxic conditions, a characteristic feature of the lung tumor microenvironment." (PMID 40458414, 2025). "The association between PYGB and TGFB1, a pivotal cytokine in the regulation of immune responses and tumor progression, further emphasized the potential role of PYGB in fostering a tumor-supportive microenvironment." (PMID 40458414, 2025). "In summary, PYGB potentially contributed to the pathogenesis of LC by influencing both tumor cells and tumor-infiltrating immune cells." (PMID 40458414, 2025). "For further analysis, GSE32863 and GSE44077 data sets were analyzed in the GEO database, and the expression of PYGB in tumor tissue was significantly higher than in normal tissue, which was consistent with the finding." (PMID 40458414, 2025). "We first used the TCGA and TARGET databases to reveal that PYGB exhibits elevated expression levels in many tumor samples when compared to normal tissues." (PMID 40458414, 2025). "Brain glycogen phosphorylase (PYGB) facilitates the breakdown of glycogen, thereby supplying energy to tumor cells." (PMID 40458414, 2025). "According to in vitro experiments, immunohistochemical (IHC) analysis found that the PYGB protein level significantly increased in LC tissues when compared to adjacent non-tumor tissues." (PMID 40458414, 2025). "Immunohistochemical evaluation confirmed markedly increased CHMP4C and PYGB expression in LUSC compared with adjacent non-tumor tissues (P < 0.001), while CAMK2A expression was significantly enriched in normal tissues (P < 0.001)." (PMID 41180485, 2025). "The relationship between PYGB expression and various immune cell types in LC is an intriguing area of study, particularly given the complex interactions between tumor cells and the immune system." (PMID 40458414, 2025). "PYGB expression was significantly elevated in tumor tissues compared to normal controls across both subtypes: LUAD (TCGA-LUAD: 513 tumors vs. 379 normal) and LUSC (TCGA-LUSC: 486 tumors vs. 379 normal)." (PMID 40458414, 2025). "In contrast, CHMP4C and PYGB were overexpressed in LUSC and associated with poor outcomes, implying roles in tumor progression and metastatic potential." (PMID 41180485, 2025). "Brain glycogen phosphorylase (PYGB) breaks down glycogen and provides an energy source for tumor cells." (PMID 38483604, 2024). "The findings showed a significant correlation between poor prognosis and elevated PYGB expression in various tumor types." (PMID 38483604, 2024). "The study revealed a significant increase in tumor weight and volume in nude mice following PYGB upregulation compared to the control group." (PMID 38483604, 2024).
tumor (continued). "We found that the mRNA level of PYGB was significantly elevated in tumor vs. normal tissues for most malignant tumors." (PMID 38483604, 2024). "To investigate the role of PYGB in tumor progression, we first analyzed PYGB expression in different malignancies in TCGA cohort." (PMID 33324633, 2020). "It was shown that PLGY were overexpression in CCRCC tumor tissue compared to its adjacent normal tissue and PYGB were overexpression in CHRCC tumor tissue compared to its adjacent normal tissue and PYGB." (PMID 32127786, 2020). "Consistently, IHC staining showed that the expression of PYGB and Ki67 in tumor tissues from ShPYGB group was much lower in comparison with that in ShCtrl group." (PMID 33324633, 2020). "Emerging evidence has hinted that PYGB, the number of glycogen phosphorylase family, participates in tumor progression." (PMID 33324633, 2020). "In nude tumor-bearing xenograft mouse model, we found that knockdown of PYGB markedly suppressed tumor growth." (PMID 33324633, 2020). "Higher levels of PYGB protein expression were observed in HCC tumor tissues compared with that in adjacent non-tumor samples." (PMID 33324633, 2020). "Compared with that in adjacent non-tumor liver tissues, PYGB protein was highly expressed in HCC tissues." (PMID 33324633, 2020). "PYGB’s role in sustaining tumor cell autonomy might reduce dependence on stromal support and driving purity." (PMID 40458414, 2025). "The observed positive correlation between PYGB and TNFSF9 (also known as 4-1BBL), a co-stimulatory molecule that enhances T-cell proliferation and survival, suggested that PYGB might be involved in modulating T-cell responses within the tumor microenvironment." (PMID 40458414, 2025). "Additionally, it was discovered that the PYGB expression of normal and tumor tissues in LUAD and LUSC differed significantly." (PMID 40458414, 2025). "Furthermore, PYGB expression was positively associated with CD276 (also known as B7-H3), an immune checkpoint molecule implicated in the inhibition of anti-tumor T-cell responses." (PMID 40458414, 2025). "Notably, CAMK2A exhibited higher expression in normal lung tissues, whereas CHMP4C and PYGB were markedly overexpressed in LUSC, with their dysregulation associated with poorer clinical outcomes and a potential role in tumor progression and metastasis." (PMID 41180485, 2025). "Finally, we investigated the influence of PYGB on the tumor immune infiltration microenvironment in LC." (PMID 40458414, 2025). "These genes include PYGB, and the low-level amplification of PYGB may be related to the epigenetic mechanism of smoking for tumor occurrence." (PMID 38334681, 2024). "In addition, according to some research, PYGB is the major isomer of GP present in tumor, fetal, and heart tissues." (PMID 38334681, 2024). "The depletion of PYGB also inhibits tumor growth in xenograft tumors and lung metastasis." (PMID 38334681, 2024). "Furthermore, The orthotopic tumor model demonstrated that knockdown of PYGB inhibited tumorigenesis, with smaller tumor size and lower tumor weight in shPYGB group." (PMID 33324633, 2020). "We detected these three glycogen phosphorylases in CCRCC and CHRCC to clarify the different mechanisms underlying glycogenolysis in the two tumor types Western blotting confirmed that PYGL was mainly upregulated in CCRCC and PYGL downregulation and PYGB upregulation were the features of CHRCC." (PMID 32127786, 2020). "Furthermore, PYGB’s positive correlation with HMGB1, a protein involved in regulating inflammation and immune responses, suggested its potential involvement in the inflammatory processes associated with tumor progression." (PMID 40458414, 2025). "The negative correlation of PYGB with these CD8+ T cell subsets suggested that higher PYGB expression might be associated with reduced CD8+ T cell activity or infiltration, potentially leading to a less effective immune response against the tumor." (PMID 40458414, 2025).
tumor (continued). "Moreover, the positive relationship between PYGB and CX3CL1, a chemokine involved in recruiting immune cells to the tumor site, indicated that PYGB might influence the infiltration of immune cells into the tumor microenvironment." (PMID 40458414, 2025). "Furthermore, silencing PYGB inhibited the tumor growth and metastasis in vivo." (PMID 33324633, 2020). "The expression of PYGB was significantly correlated with ADORA2A, a gene integral to the adenosine signaling pathway, which is critical for immunosuppression within the tumor microenvironment." (PMID 40458414, 2025). "Analysis of 21 paired LUSC tumor and adjacent normal tissues revealed that CHMP4C and PYGB were predominantly localized to the nucleus and cytoplasm of tumor cells, with positive immunoreactivity indicated by brown staining." (PMID 41180485, 2025). "After immunohistochemical analysis, it was found that the PYGB protein levels, as determined by the value of IOD, were significantly elevated in LC tissues when compared to adjacent non-tumor tissues." (PMID 40458414, 2025). "This suggests that we can predict the prognosis and tumor immunity of LUAD through the potential signature consisting of six NRGs, including PYGB." (PMID 38334681, 2024). "Studies have shown that PYGB is highly expressed in HCC tissues, and that its overexpression is related to the invasive tumor phenotype and poor prognoses of HCC patients." (PMID 38334681, 2024). "Our prognostic signature consists of five genes, PYGB, IFNGR2, TICAM1, STAT6, and VPS4B, each of which plays a critical role in necroptosis and tumor progression." (PMID 36936916, 2023). "Knockdown of PYGB inhibited HCC cell proliferation, migration, and invasion in vitro and suppressed HCC tumorigenesis in xenograft tumor model." (PMID 33324633, 2020). "Overall, the negative correlations between PYGB and these various immune cell types in LC highlighted the potential role of PYGB in modulating the immune landscape of the tumor microenvironment." (PMID 40458414, 2025). "The positive correlation between PYGB and TNFSF4 (also known as OX40L), a co-stimulatory molecule that enhances T-cell activation and survival, suggested its potential role in modulating T-cell responses and promoting anti-tumor immunity." (PMID 40458414, 2025). "The results showed that the expression levels of PYGB, IFNGR2, TICAM1, STAT6 and VPS4B in CHOL tissues showed an overall upward trend compared with non-tumor hepatobiliary duct tissues." (PMID 36936916, 2023). "Based on the heterogeneity between mRNA expression and protein expression of genes, we further examined the protein expression of PYGB in HCC tissues using ZZU HCC cohort containing 324 paired HCC tumor and adjacent non-tumor samples." (PMID 33324633, 2020). "Moreover, high PYGB expression was observed in HCC patients with advanced TNM stages, poor differentiation, large tumor size and vascular invasion." (PMID 33324633, 2020). "Additionally, proteins involved in the regulation of the cell cycle (e.g., ATM and STAT3), cell proliferation (e.g., LYN and SRRT), metabolism (e.g., GOT2, PPP1CA, and PYGB), and the regulation of Ca2+ flux (e.g., ANXA6 and CALM1) were also found phosphorylated in the tumor cells." (PMID 40129242, 2025). "The negative correlation of PYGB with these cell types suggested that PYGB might be involved in creating an immunosuppressive environment that hinders the activation and function of these cells, thereby facilitating tumor progression." (PMID 40458414, 2025).
cardiovascular diseases (1 paper, 2024). "Due to the limited predictive power of PYGB alone for cardiovascular disease, further studies may consider its use in combination with other markers." (PMID 38334681, 2024). "In summary, we need more research to prove whether PYGB can be used to identify cardiovascular disease." (PMID 38334681, 2024).
neurodegenerative disease (1 paper, 2019). A disorder of the central nervous system characterized by gradual and progressive loss of neural tissue and neurologic function. "Although our mechanism findings of miR-338-3p on PYGB are generated from Neuro2a cells in vitro, these results provide novel clues for illuminating metabolic dysfunctions in neurodegenerative diseases, and afford opportunities for consequent studies in vivo." (PMID 31133799, 2019).
PYGB also shares sentences with these, for which no sentence is quoted: acute coronary syndrome (2 papers); gastric adenocarcinoma (2); glioma (2); Lung Squamous Cell Carcinoma (2); renal cell carcinoma (2); Type 2 Diabetes (2); acute myocardial infarction (1); amyotrophic lateral sclerosis (1); brain tumors (1); colon cancer (1); diabetes (1); emphysema (1); head and neck squamous cell carcinoma (1); Hyperglycemia (1); hypertensive disorder (1); Hypoglycemia (1); Left ventricular diastolic dysfunction (1); lysosomal storage disorder (1); metabolic disease (1); nervous system diseases (1); pancreatic adenocarcinoma (1); papilloma (1); prostate adenocarcinoma (1); Sepsis (1); stomach cancer (1); urothelial carcinoma (1); urothelial papilloma (1).